IL16 (interleukin 16)
Diseases named in the same sentence as IL16 in open-access papers (continued):
Sharing a sentence is not in itself a finding about the gene and the disease.
tumor (continued). "A significant correlation was found between tumor height and several cytokines, including β-NGF, CTACK, Eotaxin, IFN-γ, IL-16, IL-1α, IL-1ra, IL-6, IL-8, M-CSF, MCP-1, MIP-1α, and SCGF-β." (PMID 41048959, 2025). "We identified IL16 and IRF4 to be broadly downregulated in tumor-infiltrating DCs, CXCR4 to be broadly upregulated, and IL18 and IL22RA2 increases to be associated with cDC2s." (PMID 39932553, 2025). "Although the effect of MLN8237 on CT26-derived tumor growth differs from that of Aurora-A knockdown, the combination treatment of MLN8237 with anti-IL-16 antibodies enhances its therapeutic efficacy." (PMID 38291041, 2024). "IL-16 is a pro-inflammatory cytokine that recruits and activates immune cells such as CD4+ T cells, monocytes, and eosinophils, which can contribute to a tumor-promoting microenvironment." (PMID 39201599, 2024). "Specifically, alterations in cytokines such as IL32, IL22, IL17F, IL17A, IL16, IL15, and HMGB1 can create an immunosuppressive tumor microenvironment in CTCLs to facilitate immune evasion and tumor progression." (PMID 39409988, 2024). "Within the tumor microenvironment, IL-16 can attract CD4+ T cells and other immune cells to the tumor site, promoting both pro-tumorigenic and antitumorigenic effects." (PMID 39408600, 2024). "Tumour-derived exosomes released by various tumour cells induce the expansion and immunosuppression of MDSCs through exosomal proteins, such as PGE2, TGFβ, Hsp72, IL-10, or IL-16." (PMID 38893071, 2024). "Similarly, the upregulation of IL-16, a chemotactic cytokine, could attract immune cells to the tumour microenvironment, potentially enhancing anti-tumour responses, and IL-1β can promote immune cell activation, which may contribute to the therapeutic effects of AuNP-P3." (PMID 39682192, 2024). "TLR2, TLR4, and inflammasome inducing MR, NLRP3 can lead to tumor progression via the production of inflammatory cytokines (IL6, IL16), increased cell proliferation, and resistance to apoptosis (TNFAIP3)." (PMID 37599366, 2023). "Ten signaling pathways only existed in the lymphatic metastases, including CD22, CD45, IL16, SPP1, LIGHT, ANGPTL, GRN, ncWNT, PERIOSTIN, and NEGR, in addition to the classical ncWNT pathways that can promote tumor progression." (PMID 37221625, 2023). "M1 macrophages secrete pro-inflammatory cytokines such as IL-12, IL-16, and INF-γ, which activate inflammatory responses and participate in host innate immunity to eliminate tumor cells in the TME." (PMID 37644235, 2023). "On the contrary there was an increase in the Th2 mediators IL-4, IL-6, IL-27, soluble chemokine ligands and pro-inflammatory mediators responsible for promoting pro-tumor immune cells; MCP-1, and IL-16." (PMID 35154142, 2022). "Both TCGA and GEO data showed a good predictive value, and four genes (GIMAP6, CD80, IL16, CCR2) contributed the most to predicting tumor purity." (PMID 35280857, 2022). "M1 macrophages secrete IL-12, IL-16, INF-γ, and other proinflammatory cytokines, activating the inflammatory response and eliminating tumor cells." (PMID 33557837, 2021). "It was reported M1 macrophages can release IL-12, IL-16, INF-γ and other proinflammatory cytokines, activating the inflammatory response and eliminating tumor cells." (PMID 34885178, 2021). "When fibroblasts from tumor stage lesions were co-culture with MyLa cells, IL4 and IL16 expression was increased, which is consistent with a malignant CTCL phenotype." (PMID 33941102, 2021). "In multiplex antibody arrays assays the majority of cytokines in tumor tissue and mouse plasma were alike, with the exception of IL-16, CCL12 and CCL3 whose expression was increased in tumor tissues." (PMID 31885880, 2020). "IL16 is a cytokine that recruits CD4+ immune cells, and its downregulation in FVPTC can suggest immunosuppression in the tumor microenvironment." (PMID 31443155, 2019).
tumor (continued). "Lymphocytes also release cytokines and chemokines, such as IL-16, CCL21, and VEGFA, that attract monocytes, dendritic cells (DCs), and endothelial cells to the tumor core and invasive margin." (PMID 27129159, 2016). "IL16, produced by CD8+T cells, can stimulate the secretion of tumor-related cytokines, such as TNF-α, IL1β, IL6, and IL1516." (PMID 27703190, 2016). "Whereas in tumor-bearing mice groups, most of cytokines were decreased after LF-MF exposure, including KC, CCL1, IFN-γ, CXCL9, CXCL12, TREM-1, CCL12, IL-1rα and IL-16." (PMID 24314291, 2013). "In cancer, IL-16 attracts CD4+ cells, showing both tumor-promoting and suppressive effects." (PMID 40003544, 2025). "IL-16 is a pro-inflammatory cytokine that exerts chemotactic effects on CD4 T lymphocytes, monocytes, and eosinophils, playing a role in both the inflammatory response and tumor development." (PMID 38571956, 2024). "We also find that trNK may also recruit CD4+ Tregs via IL-16 but concomitant FAS signaling would lead to Treg apoptosis and support tumor control." (PMID 39656086, 2024). "The functional enrichment analysis revealed that tumor cells, even under chemotherapy treatment, contain proteins involved in processes like migration, cytoskeleton locomotion, and cell adhesion (ICAM, plexin, IL-16, CD40, ARPs, and ezrin)." (PMID 36611989, 2023). "Furthermore, we obtained four genes (GIMAP6, CD80, IL16, and CCR2) that had predictive advantages for tumor purity using random forest classification and random forest regression." (PMID 35280857, 2022). "IL-16, TGF-β3, CXCL9, and SCF were the best contributors to this tumor signature." (PMID 36539890, 2022). "We divided the 443 TCGA LUAD samples with complete clinical data into high and low groups according to tumor purity, and obtained CSGTPP (0.21*CCR2+ 0.06*GIMAP6+0.64*CD80+ 0.21*IL16) with LASSO regression analysis, and then divided the samples into high and low two groups." (PMID 35280857, 2022). "We observed significant negative correlations between CD68+ macrophage infiltrations in the tumor tissue and the concentrations of the cytokines eotaxin, IFN-γ, IL-1β, IL-2, IL-10, IL-13, IL-16, VEGF and factor score of component 2 (“Inflammatory Cluster”) in the CSF." (PMID 34654395, 2021). "CEA-TCB-treated tumors displayed a clear upregulation of several pro-inflammatory cytokines and chemokines [MIPα (CCL3), CXCL10, CXCL13, CXCL9, IL-16, and I-TAC (CXCL11)], an increase in intra-tumor CD3+, CD4+, CD8+ T-cells that express high levels of 4-1BB, PD-1, and upregulation of GZMB." (PMID 33330050, 2020). "Furthermore, this study also showed that the density of IL-16 expressing microvessels increased significantly with the development of OVCA and increased further as the tumor progressed to late stages." (PMID 26161406, 2015). "IL-16 and TNF-α were undetectable in all cell culture supernatants (data not shown), but was secreted in both tumour tissues (IL-16: 5337 ± 33 and 3121 ± 94 pg/ml respectively, TNF-α: 0.30 ± 0.11 and 1.07 ± 0.17 pg/ml respectively)." (PMID 26183281, 2015). "Although there are no lymphocytes in our model, our data shows that tumor cells themselves express IL-16 and IL-17." (PMID 25400927, 2014). "On the other hand, the immune clusters were the primary recipients of signaling from the tumor clusters, whereas the normal area activated various immune-related signaling pathways (including COMPLEMENT, CCL, CXCL, and IL16), which were not received by tumor clusters." (PMID 39505867, 2024). "Mechanically, tumor-intrinsic Aurora-A promotes the cytotoxic activity of CD8+ T cells in immune hot CRC via negatively regulating interleukin-16 (IL-16), and the upregulation of IL-16 may impair the therapeutic effect of Aurora-A inhibition." (PMID 38291041, 2024).
tumor (continued). "In contrast, other pathways prominently change their information flow at PBMC or normal as compared to tumor tissue: (i) turn off (BAG), (ii) decrease (such as BAFF, FLT3, and IL1), (iii) turn on (such as GAS and LIGHT), or (iv) increase (such as MIF, PARs, ANNEXIN, and IL16)." (PMID 35812372, 2022). "It is worthwhile noting that a large panel of cytokines including MCP-1, M-CSF (CSF-1), IL-3, IL-10, IL-12, IL-16, MIP-1β, RANTES, TNF-α and TGF-β2 were upregulated resulting from autocrine effect in POSTN-overexpressing SKOV3 cells leading to potent enrichment of TAMs in the tumor microenvironment." (PMID 36550569, 2022). "A difference was found between male mice with and without primary tumor differed in IL-10 and IL-16 levels, which were higher in those with tumor, and in CXCL5, CXCL11, CXCL13, CXCL16, and CCL24 levels, which were higher in those without tumor." (PMID 32545680, 2020). "IL-6 and IL-8 (gray arrows) together with IL-16, IL-17, and IL-17E (white filled arrows) expression profiles differentiated HPV positive and negative tumor cells in vivo." (PMID 25400927, 2014).
cancer (52 papers, 2013 to 2026). A tumor composed of atypical neoplastic, often pleomorphic cells that invade other tissues. "IL-16 SNPs have been implicated in several cancers, with the G allele of rs11556218 associated with an increased risk of gastric, lung, oral, and ovarian cancers." (PMID 40003544, 2025). "Loss of nuclear IL-16 in cancer cells has been associated with increase in cytoplasmic IL-16, which has been considered to act as a growth factor for malignant T cells, and also was associated with decreased rate of cancer transformed cell apoptosis." (PMID 40529362, 2025). "The rs1131445 SNP has been linked to colorectal and cervical cancer, with carriers of the rs1131445 C allele showing higher serum IL-16 levels." (PMID 39408600, 2024). "It has been extensively studied for its role in immune response; IL-16 bioactivity has also been associated with the progression of some cancers." (PMID 38607023, 2024). "Several studies have indicated that polymorphisms of IL-16 are correlated with chronic inflammatory diseases and cancers." (PMID 38291041, 2024). "Cytokine gene single nucleotide polymorphisms (SNPs) of interleukin (IL)-1β, IL-4, and IL-16 genes have been reported to be associated with the risk of cancers, including renal cell carcinoma, gastric carcinoma, and lung cancer." (PMID 36034203, 2022). "SNP rs11556218 of IL16 was statistically associated with the risk of cancer in Chinese (T vs. G; Pooled OR = 1.38; 95% CI 1.23–1.56; random model)." (PMID 32934782, 2020). "The SNP rs11556218 of IL16 was significantly associated with an increased risk of cancer or CVD in Chinese." (PMID 32934782, 2020). "The IL16 rs11556218 polymorphism was significantly associated with the risk of cancer in Chinese, in different models of genetic inheritance." (PMID 32934782, 2020). "A current meta-analysis has concluded a positive relationship between IL-16 rs1131445 C/T and cancer risk in Asian populations." (PMID 30671474, 2018). "In the other hand, many issues addressed the major role of IL-16 polymorphism in risk of various kinds of cancers." (PMID 29564064, 2018). "IL-16 has been implicated in several cancers including OVCA." (PMID 35497879, 2022). "Similarly, IL-16 activity was found to be associated with disease progression in many cancer types, including those of the gastrointestinal tract." (PMID 36230884, 2022). "Thus, we conducted a systematic review and meta-analysis to evaluate possible associations between IL16 rs4778889, rs11556218, rs4072111, and rs1131445 SNPs and the risk for cancer or CVD." (PMID 32934782, 2020). "Thus, in this study we performed a systematic review and meta-analysis to evaluate and update information on possible correlations between the polymorphisms rs4778889 T>C, rs11556218 T>G, rs4072111 C>T, and rs1131445 T>C of IL16 and the risk of cancer or CVD." (PMID 32934782, 2020). "Furthermore, several studies have indicated that variations in IL-16 are associated with cancer risk." (PMID 30671474, 2018). "Additionally, they suggest that IL-8 and IL-16 SNPs may influence CC risk differently than other cancers, likely due to the specific relationship of CC carcinogenesis with HPV." (PMID 40003544, 2025). "Interleukin-8 (IL-8) and Interleukin-16 (IL-16) are chemokine-like interleukins involved in the pathogenesis of various cancers." (PMID 40003544, 2025). "Increased levels of IL-16 are found in the circulation and at the sites of inflammation, infection and cancer." (PMID 40529362, 2025). "Reports indicate that same types of cells express and secrete IL-16 in various categories of human diseases including infectious, inflammatory diseases and cancers." (PMID 40529362, 2025). "Extracellular IL-16 in cancer patients is a potent chemoattractant of immune cells and that IL-16 participates in development of immunotolerance to malignant cells, since inhibition of IL-16 improved prognosis in those models." (PMID 40529362, 2025).
cancer (continued). "In those hot tumors, targeting Aurora-A can suppress cancer cell growth but attenuate antitumor immunity by upregulating IL-16 expression." (PMID 38291041, 2024). "IL-16 is a multifunctional cytokine that plays a fundamental role in inflammatory diseases and the development and progression of various cancers." (PMID 36771338, 2023). "Evidence of increased IL-16 levels in serum or plasma has also been recognized in multiple malignant tumors in both preclinical and clinical trials." (PMID 36034203, 2022). "The level of IL-16 in serum is also elevated in patients with other types of cancer, especially in patients with advanced cancer." (PMID 36034203, 2022). "From the cirrhosis to cancer, IL16 and related ligand-receptor interaction (IL16-CD4) exhibited a significant difference in macrophage-naïve CD4 + T cell interaction." (PMID 36221095, 2022). "Specifically, exposure of rats to PM2.5–10 from LAC for 1–3 months was found to trigger the expression of inflammatory stress- and cancer-related biomarkers, including upregulation of IL16, IL13-Rα1, and EGR2 genes in the brain." (PMID 32211584, 2020). "Of the 23 immune-related prognostic genes identified in LUAD, 7 were reported to be associated with the progression of NSCLC or other cancers, such as ICAM3, MS4A1, and IL-16." (PMID 32209727, 2020). "The IL16 gene codes for interleukin-16, a cytokine with known roles in cancer development and inflammatory and autoimmune responses." (PMID 30832275, 2019). "The negative regulator SOCS3 is a key player in the modulation of the JAK/STAT signaling that control a number of inflammatory cytokines such as IL6 and IL16 and is involved in infectious diseases and cancers." (PMID 28179578, 2017). "Mast cells play a key role in the pathogenesis of cardiovascular diseasesand cancers via secreting a variety of cytokines includingTNF-α, IL-3, IL-4, IL-5, IL-6, IL-10, IL-13, IL-14 and IL-16." (PMID 26625310, 2016). "The role of IL-16 in cancer has been well studied in hematological malignancies, where its levels are elevated compared to healthy individuals." (PMID 26361584, 2015). "The combination of Aurora-A inhibitors and anti-IL-16 antibodies may serve as an effective strategy for cancer therapy in the future." (PMID 38291041, 2024). "It has been reported that pro-IL-16 undergoes cleavage into mature IL-16 by activated caspase-3, and previous reports indicate that inhibition of Aurora-A can activate caspase-3 in cancer cells." (PMID 38291041, 2024). "In addition, IL-16 a multifunctional cytokine that plays a key role in inflammatory diseases, as well as in the development and progression of various cancers, e.g., breast and gastrointestinal cancers." (PMID 36771338, 2023). "IL-16, as a multifunctional cytokine, plays a role in regulating immune cell functions in cancer." (PMID 37425011, 2023). "In the present study, we have shown that the intake of carrot juice decreased the secretion of a central cytokine in inflammation related to cancer development: IL-1α and IL-16 in blood samples stimulated with LPS ex vivo, although only one sample was obtained from each subject." (PMID 36771338, 2023). "This assumption is supported by one of the observations of this study that treatment of normal OSE cells with human recombinant FSH for 24 hours resulted in remarkable increase in nuclear expression of IL-16 with similarities in patterns of expression by OVCAR3 cancer cell lines." (PMID 35497879, 2022). "As we found levels of the cytokines CCL5, CXCL9, CXCL10, and IL16 to indicate high CTL score across multiple cancers, we hypothesized that ATM in its role as a signal transducer may be promoting the transcription of these cytokines." (PMID 29615613, 2018). "Importantly, our results suggest that combining Aurora-A inhibitors with IL-16-neutralizing antibodies may represent a novel and effective approach for cancer therapy, particularly in tumors with high levels of lymphocyte infiltration." (PMID 38291041, 2024).
cancer (continued). "Furthermore, whether anti-IL-16 antibodies can become effective cancer therapy drugs needs further investigation." (PMID 38291041, 2024). "In addition, some reports have shown that IL-16 is overexpressed in several cancers." (PMID 38291041, 2024). "In addition, CCL2 and IL-16 produced by MSCs have been shown to influence the survival of cancer cells in many types of cancer, including hematological malignancies, and their plasma levels were found to be elevated in AML and other hematological malignancies patients." (PMID 37932837, 2023). "Additionally, cytokine produced by M2 macrophages could also directly act on HCC cells to transform them into cancer stem cells through IL16/STAT3 signaling pathway, and promote their migration by CCL22‐CCR4 interaction." (PMID 36680322, 2023). "However, the role of IL‐16 in cancer development and progression is still under investigation." (PMID 32994998, 2020). "IL-16′s role in most cancers is still debated, but in CTCLs, it has been proven to promote cell growth by decreasing p27(KIP1) levels, while the overexpression of the secreted IL-16 molecule induces proliferation in CTCL T cells." (PMID 38607023, 2024). "Cancer-related genes MUC1, FN1, and S100-family members were the most clinically relevant in CPTC, while APLN and IL16, both immune-related, were clinically relevant in FVPTC." (PMID 31443155, 2019). "Of these six genes, we found four to be significantly correlated with CTL levels across nearly all cancer lineages: CXCL9, CXCL10, CCL5, and IL16." (PMID 29615613, 2018). "In particular, growth-regulated protein (GRO), ENA-78/CXCL5, TIMP-2, and leptin were strongly up-regulated in malignant seroma, whereas IGFBP-1 (insulin-like factor binding protein-1), IL-3, IFN-γ, FGF-9 and IL-16 were down-regulated in malignant versus benign seroma fluid." (PMID 26361584, 2015). "In addition, we also found that the presence of HDAC7 led to the upregulation of genes related to immune processes (IL16, FCGR2A, IRAK2, CD86 and CD40, among others) and cancer (RASSF4, RAB31, NEDD9 and RASSF2, among others)." (PMID 25675295, 2015). "Many studies have suggested that IL-16 transduces a signal through its receptor CD4, which serves a variety of biological functions such as a growth factor of T cells and a differentiation factor of inflammatory response cells, and has been correlated with several forms of cancer diseases." (PMID 26544695, 2015).